CXCL8 (C-X-C motif chemokine ligand 8)
Diseases named in the same sentence as CXCL8 in open-access papers (continued):
Sharing a sentence is not in itself a finding about the gene and the disease.
atherosclerosis (continued). "Based on experimental animal studies, the inhibition of chemoattractants such as CXCL2 and CXCL8 might lead to the resolution of inappropriate neutrophil mobilization and NETs induction, leading to the improvement of vasculitis and atherosclerosis." (PMID 34163363, 2021). "CXCL8 (IL-8), a CXC chemokine is also induced by LPS, stimulates the adhesion of monocytes to endothelial cells and has also been linked to the development of early atherosclerosis." (PMID 16566827, 2006). "Thus, we proposed that CXCL1 and CXCL8 might be two effectors of the protective role of PCB2 in atherosclerosis progression." (PMID 38679696, 2024). "Thus, CXCL8 may influence the development of atherosclerosis via the inhibition of cholesterol efflux protein ABCA1 thereby promoting the development of foam cells." (PMID 33503867, 2021). "In this study, we discovered the overexpression of lnc-SLC15A1-1 activation in HUVECs treated with HG + IS and the subsequent upregulation of CXCL10 and CXCL8 genes and proteins, which might explain the connection between endothelial injury and atherosclerosis." (PMID 34941711, 2021). "Indeed, the chemokines growth-related oncogene (GRO)-α/CXCL1 interleukin (IL)-8/CXCL8 and monocyte chemoattractant protein (MCP)-1/CCL2 have all been implicated in the pathogenesis of atherosclerosis, at least partly through their ability to attract and activate leukocytes into the vessel wall." (PMID 22815786, 2012). "Seven core targets-IFNG, CXCL8, TNF, TGFB1, IL2, IL4, and RELA-were identified via network pharmacology, involving key pathways such as lipid-atherosclerosis, AGE-RAGE, and IL-17 signaling." (PMID 40708520, 2026). "Our findings are consistent with prior studies demonstrating that blockade of the CXCL-8/CXCR2 axis limits monocyte transmigration and lesion development in early atherosclerosis." (PMID 41280941, 2025). "The core targets correspond to 18 pathways, CXCL8, CY1A2, FOS, and other targets correspond to multiple pathways, and the most corresponding pathway is lipid and atherosclerosis pathway." (PMID 38905402, 2024). "This activates M1-type macrophages which produce chemokines, namely CCL2, IL6, CXCL8, CXCL2, and CXCL20, leading to a complex cascade that encourages atherosclerosis." (PMID 39634983, 2024). "A key aspect of atherosclerosis is the oxidation of LDL which is recognized by the immune system as a danger signal and results in the release of CXCL8." (PMID 33503867, 2021). "In fact, an interesting paper reported an induction of IL-8 (CXCL8) in response to cholesterol loading in macrophages foam cells, one of the hallmarks of atherosclerosis." (PMID 30254608, 2018). "Several chemokines including CXCL1/growth-related oncogene (GRO)-α, CXCL8/interleukin (IL)-8 and CCL2/monocyte chemoattractant protein (MCP)-1 are important in the pathogenesis of atherosclerosis and can be influenced by statin-treatment." (PMID 22815786, 2012). "BBG-NEs may promote wound healing by affecting IL-17, AGE-AGEs, and lipid and atherosclerosis signaling pathways as well as pivotal targets like AKT1, CXCL8, and EGFR." (PMID 38731484, 2024). "Measurement of cytokines and proteases in the supernatants of HAoSMCs confirmed that inflammatory mediators, such as CXCL8, IL-6, IL-1β, and IL-1α and proteases, such as MMP-10 [role in atherosclerosis and vascular calcification], were produced and released by HAoSMCs upon aging in vitro." (PMID 34313809, 2021). "CXCL8 interacted with its receptor CXCR2 on neutrophils, leading to the formation of NETs via Src and extracellular signal-regulated kinase (ERK) and p38 mitogen-activated protein kinases (MAPK) signaling to aggravate atherosclerosis progression in vivo." (PMID 33503867, 2021). "Chemokine IL-8/CXCL8 is known to play an important role in the migration of monocytes into the subendothelial space in the early phase of atherosclerosis, and along with MCP-1/CCL2, plays an important role in the pathogenesis of atherosclerosis." (PMID 20107546, 2009).
atherosclerosis (continued). "IL6, CXCL8, CCL2, SOD2, NFKBIA, and BIRC3 were identified as the top 6 hub genes in the magenta module (human cardiomyocyte samples) and were mainly enriched in the NOD-like receptor signaling pathway, IL-17 signaling pathway, TNF signaling pathway, lipid and atherosclerosis signaling pathway." (PMID 36426222, 2022). "In an in vitro study, CXCL8 enhances the expression of miR-183, which then inhibits ABCA1 expression and cholesterol efflux, suggesting that the CXCL8-miR-183-ABCA1 axis may play an transitional role in the development of foam cells in atherosclerosis." (PMID 33503867, 2021). "Thus, the combination of previous and current research results revealed that TNF, CXCL8, SOCS3 and TNFAIP3 may be involved in chronic inflammatory lesions that eventually result in atherosclerosis, CAD or IS." (PMID 32164735, 2020). "Furthermore, CXCL8 involved in the regulatory process of NEAT1, a long non-coding RNAs, on atherosclerosis." (PMID 36062083, 2022).
colon carcinoma (230 papers, 2002 to 2025). "The senescence-associated genes CDKN2A and CXCL8 were significantly downregulated in colon cancer cells after shikonin treatment." (PMID 39188951, 2024). "We found that shikonin increased the activity of senescence-associated β-galactosidase (SA-β-Gal) in colon cancer cells after downregulation of CXCL8 and CDKN2A through a senescence-associated β-galactosidase (SA-β-Gal) staining experiment." (PMID 39188951, 2024). "Network analyses were carried out using the Amadis database analysis tool, and a possible association between CXCL8, Fusobacterium nucleatum, and human diseases (including inflammatory bowel disease and colon cancer) was found." (PMID 34439306, 2021). "CXCL8 constitutive expression in human colon carcinoma cell lines has been linked to the metastatic potential in immunodeficient transgenic mice models, thus suggesting a role of CXCL8 in the development of distant metastases from colorectal tumours." (PMID 31986121, 2020). "In colon cancer, CXCL8 is implicated in cellular proliferation, invasion, and metastasis." (PMID 38791448, 2024). "Other studies found that CXCL8 is closely associated with the progression of colon cancer, and the inhibition of P16INK4a expression also reduced the expression of CXCL8." (PMID 39188951, 2024). "Likewise, we detected the colon cancer prognostic biomarker CXCL8 and its associated pro-inflammatory cytokines (IL1-β, TNF-α, IFN-γ and IL-6) in the serum of mice in each group." (PMID 35922850, 2022). "CXCL8 expression within the stromal compartment was associated with reduced cancer‐specific survival in the first cohort (p = 0.035), and this relationship was potentiated in right‐sided colon cancer cases (p = 0.009)." (PMID 35879507, 2022). "CXCL8 is significantly associated with infiltration of CD8+ T cells in colon cancer." (PMID 36532065, 2022). "With the aid of network analysis tools of the Amadis database, we found that there could be an association between CXCL8, Fusobacterium nucleatum, and human diseases (including inflammatory bowel disease and colon cancer)." (PMID 34439306, 2021). "In colon cancer, CXCL8 promotes M2 macrophage polarization by activating the STAT3 signaling pathway and upregulating PD-L1 expression in M2 macrophages while simultaneously reducing T cell infiltration." (PMID 40270974, 2025). "We then investigated which transcription factor cooperates with SKAP1 to enhance CXCL8 expression in colon cancer cells." (PMID 39269257, 2024). "By activating the PI3K/Akt/NF-κB signaling pathway, CXCL8 can induce epithelial–mesenchymal transition, promoting colon cancer progression." (PMID 38791448, 2024). "In conclusion, SKAP1 significantly promotes colon cancer growth via the cancer cell/neutrophil NFATc1/CXCL8/NET axis, suggesting that SKAP1 is a potential target for colon cancer therapy." (PMID 39269257, 2024). "Systemic reparixin treatment largely attenuated the tumor‐promoting effect of SKAP1 and completely abolished SKAP1‐associated infiltration of neutrophils in HCT116 tumors, suggesting that SKAP1 promotes neutrophil infiltration into colon tumors via CXCL8." (PMID 39269257, 2024). "Both reparixin and CXCL8‐neutralizing antibodies efficiently inhibited the NET‐enhancing effect of CM from SKAP1‐overexpressing colon cancer cells." (PMID 39269257, 2024). "Molecular docking analysis revealed that shikonin promotes cellular senescence in colon cancer cells by blocking the activity of CXCL8 at the protein level." (PMID 39188951, 2024). "EGCG inhibits NET formation by regulating the STAT3/CXCL8 signaling pathway, which further suppresses the colon cancer cells’ invasion and migration." (PMID 39201782, 2024). "Molecular docking revealed that shikonin suppressed colon cancer progression by blocking CXCL8 activity." (PMID 39188951, 2024). "Among the downregulated genes, we selected CDKN2A and CXCL8 as targets to further explore their roles in colon cancer progression." (PMID 39188951, 2024).
colon carcinoma (continued). "By controlling the PI3K/AKT/NF-κB signaling pathway, CXCL8 overexpression speeds up the epithelial–mesenchymal transition and the malignant phenotype of colon cancer cells." (PMID 39201782, 2024). "Through the analysis of each gene on the prognosis of colon cancer through the GEPIA online analysis website, it was found that the expression levels of AQP8, CXCL8, and ZG16 genes were remarkably associated with colon cancer prognosis (P < 0.05)." (PMID 37954103, 2023). "This study confirmed the role of CXCL8 and LSECtin in immune microenvironment modulation of colon cancer." (PMID 36358719, 2022). "Later, we demonstrated that CXCL8 up-regulated LSECtin expression by activating AKT signal in colon cancer cells." (PMID 36358719, 2022). "The results showed that the expression of CXCL8 in colon cancer was significantly higher than that in normal mucosa." (PMID 36358719, 2022). "This study evaluated the role of CXCL8 and LSECtin in the immune microenvironment and ICIs efficacy prediction of colon cancer, and clarified the regulatory mechanism of CXCL8 regulating LSECtin through AKT activation." (PMID 36358719, 2022). "There was a significant positive correlation between the expression of CXCL8 and LSECtin in colon cancer." (PMID 36358719, 2022). "In order to clarify the correlation between CXCL8 and LSECtin in colon cancer, we performed the analysis in the TIMER database and found that there was a significant positive correlation between CXCL8 and LSECtin expression (r = 0.357, p = 3.24 × 10−15)." (PMID 36358719, 2022). "IL-8/CXCL8 was found to be regulated by JNK/MAPK8 in colon cancer and became a downstream signal pathway of tumor regrouping induced by necroptosis." (PMID 35237304, 2022). "Our results showed that CXCL8 expression is positively correlated with LSECtin expression in colon cancer." (PMID 36358719, 2022). "Our results showed that the expression of LSECtin was closely related to the activation of CXCL8/CXCR1/2 signal axis in colon cancer." (PMID 36358719, 2022). "In conclusion, this study is the first to clarify the regulatory effect of CXCL8 on LSECtin, which is an important mechanism for CXCL8 to regulate the immune microenvironment of colon cancer." (PMID 36358719, 2022). "First, we analyzed the different expression of CXCL8 and LSECtin in colon cancer and the main biological functions involved." (PMID 36358719, 2022). "Data from vitro and clinical studies also suggested that the activation of CXCL8/CXCR1/2 signal axis is an important factor in regulating the immune microenvironment of colon cancer and leading to less benefit of ICIs treatment in colon cancer." (PMID 36358719, 2022). "Emerging clinical evidence suggests that CXCL8/CXCR1/2 signal axis plays a key role in immune escape and CXCL8 high expressed colon cancer seldom benefit from ICIs therapy." (PMID 36358719, 2022). "Recombinant human CXCL8 can significantly promote the proliferation and invasion of colon cancer cells." (PMID 36358719, 2022). "EGCG reduced STAT3 and CXCL8 expression in colon-cancer-patient-derived neutrophils to inhibit the formation of neutrophil extracellular traps and suppress colon cancer migration in vitro." (PMID 36700235, 2022). "After the AKT signal was blocked by MK2206, we found that while the role of CXCL8 in promoting the invasion of colon cancer cells was inhibited, the regulatory effect of CXCL8 on LSECtin also disappeared." (PMID 36358719, 2022). "This contradictory phenomenon reflects the complex role of CXCL8 in the occurrence and development of colon cancer." (PMID 34439306, 2021). "Results showed increased expression levels of the MYC/CXCL8/TIMP1 oncogenes across colon cancer cell lines." (PMID 34440739, 2021). "The analysis showed that the expression of CXCL8 in colon cancer was higher than in normal controls, and patients with high expression of CXCL8 in colon cancer had a longer survival time." (PMID 34439306, 2021).
colon carcinoma (continued). "The murine experiments above were validated in a human colon cancer cell line HT-29 stimulated with CXCL8, which is the human homologue of the murine CXCR2 ligand." (PMID 34115261, 2021). "A previous study in a transgenic mouse model carrying the human CXCL8 gene demonstrated accelerated growth of gastric and colon cancers through the recruitment of MDSCs." (PMID 33290281, 2021). "There are contradictory evidences in the role of CXCL8 in the development and progression of colon cancer." (PMID 34439306, 2021). "It has been reported that inhibition of CXCL8 has been found to inhibit the migration of human colon tumor cell line (HCT116 cells), so we selected HCT116 for our in vitro study." (PMID 34025668, 2021). "Colon carcinoma cells show a peculiar invasive phenotype closely coupled to CXCL8/CXCR1 signalling transduction pathway, as previously demonstrated." (PMID 31986121, 2020). "In another study, overexpression of CXCL8 induced cell proliferation, migration, and invasion of colon cancer LoVo cells, and CXCL8 induced EMT via the PI3K/AKT/NF-κB signaling axis was reported." (PMID 33240582, 2020). "CXCL8 secreted by malignant colon tumors had angiogenic effects on HIMEC (endothelial tube formation, EC chemotaxis), which was suppressed by CXCR2 antibody blockade or by ERK1/2 inhibition." (PMID 30800123, 2019). "This is in disagreement with several reports that CXCL8 is upregulated in colon cancer cells and surrounding stromal cells in comparison with its normal counterparts." (PMID 29850390, 2018). "Notwithstanding, expression of CXCL2, CXCL3 and CXCL8 is increased in colon cancer compared with normal colon tissue and CXCL2 and CXCL3 expression has been found to be already upregulated in premalignant adenomas." (PMID 30591657, 2018). "Several studies describe an upregulation of CXCL8 in colon cancer cells and surrounding stromal cells under the influence of various proinflammatory cytokines, such as IL-1β and TNF-α, and even microorganisms and hypoxia." (PMID 29850390, 2018). "This association is obviously due to the profound trophic effect of CXCL8 on human colon cancer cells along with increased peritumoral neoangiogenesis and extravasation of tumor cells into the liver and lung." (PMID 29850390, 2018). "A link between CXCL8 and the cell cycle has been reported, which further clarifies the mechanistic role of CXCL8 in colon cancer." (PMID 28881576, 2017). "Notably, recent studies have reported that specific chemokines, such as CXCL8, can enhance the proliferation, migration, and invasion of colon cancer cells by activating the PI3K/Akt/NF-κB signaling pathway, promoting epithelial–mesenchymal transition." (PMID 38791448, 2024). "Clinical validation of the SKAP1/NFATc1/CXCL8 axis in colon cancer is also required." (PMID 39269257, 2024). "We provide evidence, for the first time, that SKAP1 expression in cancer cells potently promotes the in vivo growth of colon tumors and further revealed that the cancer cell/neutrophil NFATc1/CXCL8/NET axis is the key mechanism contributing to the tumor‐promoting effect of SKAP1." (PMID 39269257, 2024). "The CXCL8-CXCR2 axis in the colon cancer microenvironment is also significant, with studies demonstrating that elevated CXCL8 levels in serum and the tumor microenvironment enhance human and murine colon cancer cell growth and support pulmonary and hepatic metastasis." (PMID 38791448, 2024). "CDKN2A and CXCL8 were highly expressed in colon cancer and various other tumors." (PMID 39188951, 2024). "The TME has a high expression of CXCL8, which encourages colon cancer growth and metastasis." (PMID 39201782, 2024). "In colon cancer cells, CXCL8 expression is inhibited by downregulating STAT3." (PMID 39201782, 2024). "Additionally, a recent report illuminated EGCG blocked NET formation as well as STAT3 and CXCL8 expression in the colon cancer-derived TANs, thereby inhibiting the invasion and migration of colon tumor." (PMID 38348027, 2024).